ADIPOR2 (adiponectin receptor 2)
Diseases named in the same sentence as ADIPOR2 in open-access papers (continued):
Sharing a sentence is not in itself a finding about the gene and the disease.
steatosis (9 papers, 2013 to 2023). Increased lipid within the cytoplasm of cells. "Adiponectin receptor 2 (AdipoR2)-deficient mice fed a methionine-choline deficient diet showed higher levels of steatosis, inflammation and fibrosis." (PMID 30374329, 2018). "In conclusion, in patients with chronic HBV, the insulin sensitizing adipokine adiponectin, and its receptor AdipoR2 were associated with steatosis." (PMID 23914225, 2013). "In a model of HCV-induced steatosis, fenofibrate rescues the expression of pAMPK and adiponectin receptor 2 (AdipoR2) by reducing ER stress and inflammatory proteins." (PMID 36724021, 2023). "The aim of the present study was to define the potential role of adipocyte-derived adiponectin, and its receptors, adipoR1 and adipoR2, in the pathogenesis of steatosis in patients with CHB." (PMID 23914225, 2013). "In subjects with steatosis, adipoR2 mRNA expression was negatively correlated with BMI (rs = -0.547, P = 0.001), and γ-GT (rs = -0.442, P = 0.009)." (PMID 23914225, 2013). "Reduced hepatic expression of adiponectin and adipoR2 might be of pathophysiological relevance in CHB patients with steatosis." (PMID 23914225, 2013). "miR-375 also targets the adiponectin receptor 2 (AdipoR2) protein, an important regulator of glucose and lipid metabolism, by activating the PPAR-α pathway, allowing it to reduce insulin sensitivity and steatosis." (PMID 37371692, 2023). "In addition, this treatment seemed to play the role of metabolic protection being capable to restore the normal level of genes expression upregulated after steatosis treatment, between them RXRA, NR1H2, CEBPB, ADIPOR2, and CYP2E1." (PMID 36770927, 2023). "While mRNA levels of adipoR1, adipoR2, and adiponectin tended to be lower in liver biopsies of subjects with steatosis compared tosubjects without steatosis, suggesting a pathophysiological role for this adipokine in liver diseases." (PMID 23914225, 2013). "AdipoR2 staining again tended to be more pronounced in liver biopsies of subjects without steatosis compared to the subjects with steatosis (2.25 ± 0.37 vs. 1.65 ± 0.29; P= 0.048)." (PMID 23914225, 2013). "The adipoR2 mRNA expression was significantly decreased in liver biopsies of patients with steatosis compared to those without steatosis (3.57 ± 0.33 vs. 7.12 ± 0.67; P = 0.000)." (PMID 23914225, 2013). "Collectively, these observations suggest that THC-ameliorated steatosis might contribute to the upregulation of AdipoR1-AMPK signaling and the AdipoR2-PPARα pathway, thus improving lipid and glucose metabolism in the liver and muscle of HFD/STZ-induced diabetic obese mice." (PMID 34960104, 2021). "FFAs treatment increased AdipoR2 levels, and such increase was strengthened by ATL III treatment, which suggested that AdioR2 maybe not involved in FFAs-induced steatosis of HepG2 cells." (PMID 35280674, 2022).
nonalcoholic steatohepatitis (7 papers, 2013 to 2025). "Activating hepatic Adipor2 could protect mice against non-alcoholic steatohepatitis, and Adipor2 deficiency could promote T2DM." (PMID 34638602, 2021). "JT003 is a synthetic adiponectin agonist against receptors AdipoR1 and AdipoR2 and has proved effective in reducing the activation of hepatic stellate cells in non-alcoholic steatohepatitis (NASH) and liver fibrosis." (PMID 40148800, 2025). "Three genes in particular, ACOT1, ADIPOR2 and ADORA1, are associated with nonalcoholic steatohepatitis." (PMID 32075112, 2020). "Rosiglitazone treatment for 8 weeks improves the histological lesions in liver of nonalcoholic steatohepatitis rats, increases mRNA and protein expressions of AdipoR1 and AdipoR2 in liver and visceral fat, with down-regulation of the two receptors in muscle." (PMID 23349663, 2013).
atherosclerosis (6 papers, 2010 to 2025). A disease characterized by the build-up of fatty material and calcium deposition in the arterial wall resulting in partial or complete occlusion of the arterial lumen. "In order to study the effects of combined AdipoR1 and AdipoR2 deficiency on atherosclerosis during ApoE deficiency, we first wanted to produce AdipoR1-/-AdipoR2-/- mice." (PMID 24324556, 2013). "We then investigated the effect of AdipoR2-ablation on the progression of atherosclerosis in apolipoprotein E deficient (ApoE-/-) mice." (PMID 24324556, 2013). "The original aim of this study was to investigate the effect of combined AdipoR1 and AdipoR2 deficiency (AdipoR1-/-AdipoR2-/-) on atherosclerosis." (PMID 24324556, 2013). "In summary, we show that adiponectin receptors are crucial during embryonic development and that AdipoR2-deficiency slows down the progression of atherosclerosis in the brachiocephalic artery of ApoE-deficient mice." (PMID 24324556, 2013). "Increased levels of AdipoR2 were observed in old WT mice when compared with NLRP3−/−, which could be associated with AdipoR2 deficiency‐dependent protection of atherosclerosis." (PMID 31625260, 2020). "Thus, it will be important for future studies to investigate the long-term consequences of AdipoR2-deficiency on atherosclerosis under more moderately elevated cholesterol levels." (PMID 24324556, 2013). "We then hypothesized that the favourable metabolic phenotype of AdipoR2-/- mice we and others have observed previously also could be associated with a protective effect against developing atherosclerosis." (PMID 24324556, 2013). "Interestingly, the progression of atherosclerosis was attenuated in the brachiocephalic artery of AdipoR2 deficient mice." (PMID 24324556, 2013). "We could also demonstrate the novel finding that AdipoR2 deficiency has a protective effect on the progression of atherosclerosis in ApoE-/- mice." (PMID 24324556, 2013). "Thus, neither plasma levels of lipids or adiponectin could help to explain the protective effect of AdipoR2 deficiency against atherosclerosis." (PMID 24324556, 2013). "AdipoR1 and AdipoR2 mediate metabolic processes and accumulation of lipids in macrophages in atherosclerosis; adiponectin demonstrated the ability to suppress lipid accumulation in macrophages." (PMID 35890325, 2022). "Thus, the decreased progression of atherosclerosis in AdipoR2-/-ApoE-/- mice was likely due to other mechanisms than decreased inflammation." (PMID 24324556, 2013). "Therefore, the decreased atherosclerosis in AdipoR2-/-ApoE-/- mice compared with AdipoR2+/+ApoE-/- controls must be explained by other mechanisms than reduced plasma cholesterol levels." (PMID 24324556, 2013). "We generated mice deficient in both AdipoR2 and ApoE (AdipoR2-/-ApoE-/-) and littermate control mice lacking only ApoE (AdipoR2+/+ApoE-/-) in order to study the impact of AdipoR2 deficiency on the atherosclerosis process." (PMID 24324556, 2013). "The mechanisms through which variations in the ADIPOR2 could influence atherosclerosis and cardiovascular disease are only hypothetical at the moment." (PMID 20178558, 2010). "Thus, downregulation of CD36 and upregulation of ABCA1 in macrophages may have contributed to the slower progression of atherosclerosis in the brachiocephalic artery of AdipoR2-/-ApoE-/- mice in the present study." (PMID 24324556, 2013). "Mice deficient in both AdipoR2 and ApoE (AdipoR2-/-ApoE-/-) and littermate control mice lacking only ApoE (AdipoR2+/+ApoE-/-) were generated to study the effect of AdipoR2 deficiency on the progression of atherosclerosis." (PMID 24324556, 2013). "Thus, considering the results from the present study, AdipoR1 and AdipoR2 signalling may have opposing effects in atherosclerosis and it will be important for the future to investigate the effect of AdipoR1 deficiency on the atherosclerosis process." (PMID 24324556, 2013).
Hepatic steatosis (6 papers, 2015 to 2025). Steatosis is a term used to denote lipid accumulation within hepatocytes. "In murine models, AdipoR2 deficiency leads to hyperinsulinemia, reduced PPAR-α activation, and increased oxidative stress and hepatic inflammation, whereas its overexpression improves glucose homeostasis, insulin sensitivity, and reduces hepatic steatosis." (PMID 41305006, 2025).
Hyperglycemia (6 papers, 2008 to 2025). An increased concentration of glucose in the blood. "When the CC genotype (-174G/C IL6) is combined with the GA + 219A/T genotype in the ADIPOR2 gene, hyperglycemia is 1.3 times more frequent than with other IL6/ADIPOR2 genotype combinations." (PMID 41010061, 2025). "When the IL6 CC genotype is combined with ADIPOR2 GA or ADIPOR2 219 A/T, hyperglycemia is 1.3 times more frequent than with other IL6/ADIPOR2 genotype combinations." (PMID 41010061, 2025). "Adiponectin acts via two receptor isoforms – AdipoR1 and AdipoR2 – that are regulated by hyperglycaemia and hyperinsulinaemia in liver and muscle." (PMID 18353182, 2008). "In addition, the good agreement between cardiac APN level and AdipoR2 expression in diabetic rats suggests that cardiac APN level may directly affects cardiac AdipoR2 expression under hyperglycemia." (PMID 21912612, 2011). "Additionally, ADPN alleviated hyperglycemia-induced downregulation of Ki-67 (a cell proliferative marker), an effect that was partially reversed by AdipoR1 knockdown but not AdipoR2 silencing." (PMID 41146365, 2025).
breast tumor (5 papers, 2015 to 2022). "Multivariable-adjusted associations of body fatness measures with ADIPOR2 protein and ADIPOR2 gene expression in breast tumor tissues." (PMID 35846306, 2022). "Subgroup analysis of the multivariate associations of LEP, LEPR, ADIPOQ, ADIPOR1, and ADIPOR2 IHC expression with breast tumor clinicopathologic features among Black women yielded similar findings." (PMID 32046756, 2020). "In the current study, we hypothesize that measures of body fatness are associated with LEPR, ADIPOR1, and ADIPOR2 expression profiles in the breast tumor microenvironment, which might contribute mechanistically to the development of more aggressive breast tumor phenotypes and poorer prognosis." (PMID 35846306, 2022). "Building on our prior research, here we examined the associations of body fatness measures with protein and gene expression of the adipokines, LEP and ADIPOQ, and the adipokine receptors, LEPR, ADIPOR1, and ADIPOR2 in breast tumor tissues." (PMID 35846306, 2022). "A representative figure shows adjacent breast tissue to tumor and breast tumor tissues labeled by indirect immunofluorescence for A) Adiponectin and B) AdipoR1 and AdipoR2 with DAPI as nuclear counterstain." (PMID 26431176, 2015). "ADIPOR2 is a receptor for adiponectin C1Q and collagen domain containing (ADIPOQ), an adipocytokine secreted by adipocytes in the breast tumor microenvironment, which negatively regulates cancer cell growth." (PMID 35739271, 2022). "Variation in LEPR IHC expression was observed by breast tumor clinicopathologic features, while the expression of LEP, ADIPOQ, ADIPOR1, and ADIPOR2 did not appear to vary by tumor clinicopathology." (PMID 32046756, 2020).
gastric cancer (5 papers, 2011 to 2025). A primary or metastatic malignant neoplasm involving the stomach. "AdipoR1 and AdipoR2 have been identified in various tissues and cell types, and their expression has been reported in human lung, breast, pancreatic, colorectal, and gastric cancer tissues." (PMID 39849382, 2025). "The upregulation of AdipoR1 and AdipoR2 are reported in gastric carcinoma, whereas decreased in prostate cancer tissues compared with the nonmalignant tissues." (PMID 27119501, 2016). "AdipoR1 and AdipoR2 expression in gastric cancer cell lines (MKN45, TMK-1, NUGC3, and NUGC4) was evaluated by western blotting analysis, and the antiproliferative potential of adiponectin was examined in vitro." (PMID 22078265, 2011). "The protein expression of AdipoR1 and AdipoR2 was confirmed by immunostaining of surgically resected gastric cancer tissue specimens." (PMID 22078265, 2011). "In this study, we evaluated expression levels of 2 adiponectin receptors--AdipoR1 and AdipoR2--and attempted to correlate their expression with prognosis in gastric cancer patients." (PMID 22078265, 2011). "Serum adiponectin levels were evaluated in 100 gastric cancer patients, and the expression of AdipoR1 and AdipoR2 was assessed by immunohistochemical staining." (PMID 22078265, 2011). "Expression of AdipoR2 and clinicopathological characteristics in gastric cancer patients." (PMID 22078265, 2011). "In addition, AdipoR2 is downregulated in human gastric cancer and endometrial adenocarcinoma." (PMID 33752745, 2021).
Impaired glucose tolerance (5 papers, 2011 to 2021). An abnormal resistance to glucose, i.e., a reduction in the ability to maintain glucose levels in the blood stream within normal limits following oral or intravenous administration of glucose. "The results of the present study suggest that independent genetic signals in the ADIPOR2 locus contribute to the risk of CVD and T2DM in a study population consisting of individuals with impaired glucose tolerance." (PMID 21943112, 2011). "The aim of this study was to investigate the role of ADIPOR2 locus variation in individuals with impaired glucose tolerance (IGT) participating in a controlled lifestyle intervention study (DPS study) with longitudinal data on metabolic and anthropometric parameters, and CVD incidence." (PMID 21943112, 2011).
coronary artery disease (4 papers, 2010 to 2022). "In this study, we investigated the association between eight common single nucleotide polymorphisms of the ADIPOR2 gene with the presence of coronary artery disease and its protein expression from human peripheral monocytes from the same individuals." (PMID 20178558, 2010). "The aim of this study was to investigate the association of ADIPOR2 gene variations with coronary artery disease (CAD)." (PMID 20178558, 2010). "Changes in the expression of AdipoR1 and AdipoR2 were described in monocytes of type 2 diabetes patients and overweight patients with coronary artery disease." (PMID 36527105, 2022). "Nevertheless, the role of genetic variants of ADIPOR2 in coronary artery disease has not been studied yet." (PMID 20178558, 2010). "Likewise, reduced monocyte AdipoR1 and AdipoR2 protein expression was observed in obese adults with coronary artery disease, compared to obese adults without cardiovascular disease." (PMID 29073286, 2017).
endometrial cancer (4 papers, 2016 to 2025). Primary or metastatic malignant neoplasm involving the endometrium (mucous membrane that lines the endometrial cavity). "The opposite associations of ADIPOR1 and ADIPOR2 with grade, histology, LVSI, and MELF underscore the complexity of these receptors' roles in endometrial cancer, warranting further exploration of their opposing functional implications." (PMID 40642843, 2025). "ADIPOR1 expression was elevated in grade 1 type 1 endometrial cancer, while ADIPOR2 was higher in type 2 cancers and showed similar levels in grade 1 and 2 cancers." (PMID 40642843, 2025). "In endometrial cancer tissues, the expression of AdipoR1 is higher than that of AdipoR2." (PMID 31440472, 2019).
hepatocellular carcinoma (4 papers, 2016 to 2023). A malignant tumor that arises from hepatocytes. "In particular, isoquercitrin elevated protein expression of adiponectin receptors such as AdipoR1 and AdipoR2 in the rat hepatoma cells." (PMID 32397362, 2020). "Moreover, a recent study showed that miR-218 targets adiponectin receptor 2 (AdipoR2) in cultured hepatoma cells, HepG2, and attenuates the adiponectin signal." (PMID 27135827, 2016).
Hyperinsulinemia (4 papers, 2017 to 2025). An increased concentration of insulin in the blood. "A previous study reported that expression of adiponectin receptor 2 in women with PCOS is downregulated by hyperinsulinemia and overweight." (PMID 29382850, 2018).
prostate carcinoma (4 papers, 2016 to 2023). A carcinoma that arises from epithelial cells of the prostate gland. "According to a study involving 866 patients, ADIPOR2 was related to lethal prostate cancer." (PMID 36896172, 2023).
cardiac hypertrophy (3 papers, 2013 to 2016). "To determine which receptor was responsible for the effect of APN on miR-133a in Ang II induced cardiac hypertrophy, we firstly detected AdipoR1 and AdipoR2 mRNA expression in NRVMs stimulated with Ang II." (PMID 26845040, 2016). "However, angiotensin II-infusion done on normal rats induced cardiac hypertrophy and reduced the expression of AdipoR1 but not AdipoR2." (PMID 27092079, 2016).
colitis (3 papers, 2018 to 2021). Inflammation of the colon. "In another DSS-colitis study, induction of colitis significantly decreased adiponectin and increased expression in both AdipoR1 and adiponectin receptor 2 (AdipoR2)." (PMID 33603741, 2020). "We have not verified what kind of ADN induced colitis in mice and the role of AdipoR2 in IBD is still unclear." (PMID 29540173, 2018).
colon cancer (3 papers, 2014 to 2021). "Knockdown of AdipoR2 relieved the suppressive effects of adiponectin on the growth of colon cancer cells." (PMID 33752745, 2021). "Results from an additional study demonstrated that adiponectin mediated AMPK activity via AdipoR1 and AdipoR2 in a colon cancer cell line." (PMID 26362652, 2015).
hypoadiponectinemia (3 papers, 2012 to 2017). "Future studies, investigating the effects of more global muscle-specific overexpression of AdipoR2 may provide further insights into the underlying mechanisms which may provide novel strategies to reverse hypoadiponectinemia and or adiponectin resistance." (PMID 28145500, 2017).
liver fibrosis (3 papers, 2020 to 2024). "A study demonstrated that AdipoR1 knockout in mice had no significant impact on hepatic fibrosis progression, whereas AdipoR2 knockout exhibited a marked increase in hepatic fibrosis, highlighting the critical role of AdipoR2 in fibrosis development." (PMID 39737222, 2024). "Binding of ADPN to AdipoR2 enhances PPARα ligand activity, promoting fatty acid oxidation, glucose utilization, and improved lipid metabolism, thereby reducing hepatic fibrosis." (PMID 39737222, 2024). "Adiponectin may also attenuate liver fibrosis by inducing nitric oxide production of hepatic stellate cells that constitutively express both AdipoR1 and AdipoR2." (PMID 35831700, 2022). "Recently, the dual AdipoR1/AdipoR2-based agonist JT003 has been demonstrated to enhance fatty acid oxidation and glucose uptake and mitigate liver fibrosis and insulin resistance in mice via signaling pathways, including AMPK, PPARα, and AKT." (PMID 39737222, 2024). "Thus, the AdipoR1/AdipoR2 dual agonist improves both NASH and fibrosis in mice models, which provides the pharmacological and biological foundation for developing AdipoRs-based therapeutic agents on liver fibrosis." (PMID 33199780, 2020).
pancreatic cancer (3 papers, 2012 to 2017). "Expression levels of AdipoR1 and AdipoR2 were also decreased in murine pancreatic cancer samples and in cell lines Panc02, P-4313, and K-8484 when compared to normal murine pancreatic tissue." (PMID 29156726, 2017). "We further characterized the mRNA expression of AdipoR1 and AdipoR2 in human and murine pancreatic tumor tissue as well as PDAC cell lines relative to normal pancreas utilizing quantitative PCR analysis." (PMID 29156726, 2017). "To determine the role of AdipoR in pancreatic cancer growth, we first tested the expression of AdipoRs using RT-PCR in H7 and Panc02 cell lines and found that both cell lines expressed AdipoR1 and AdipoR2." (PMID 25051362, 2014). "Adiponectin has two receptors, AdipoR1 and AdipoR2, both of which are highly expressed in tumor tissues of pancreatic cancer." (PMID 25051362, 2014). "Taking into consideration that experiments in mice suggest a role of AdipoR2 in pancreatic islet cell maintenance, there might be some connection between Cdh3 and Adipoq functions in the process of developing pancreatic cancer." (PMID 22291890, 2012). "We found that adiponectin significantly inhibited the apoptosis of both human and mouse pancreatic cancer cells via adipoR1, but not adipoR2." (PMID 25051362, 2014).